ASAH2B (N-acylsphingosine amidohydrolase 2B)
Synonyms: ASAH2C; ASAH2L; bA449O16.3; bA98I6.3
Tractability: Antibody: its Gene Ontology location is reachable by antibodies, with medium confidence. PROTAC: ubiquitination databases record sites on it.
Gene: Protein-coding gene on chromosome 10 (50,739,318 to 50,816,495, forward strand). Ensembl gene ENSG00000204147.
Subcellular location (Human Protein Atlas): Focal adhesion sites
Gene Ontology:
Molecular function: N-acylsphingosine amidohydrolase activity
Biological process: ceramide biosynthetic process; ceramide catabolic process; sphingosine biosynthetic process
Cellular component: cytoplasm; plasma membrane
Homologues: Orthologues: macaque ASAH2 (95% identical), dog ASAH2 (85% identical), mouse Asah2 (80% identical), rat Asah2 (78% identical), zebrafish asah2 (49% identical), tropical clawed frog asah2 (38% identical), Drosophila melanogaster CDase (29% identical). Paralogues in human: ASAH2 (99% identical).
Diseases named in the same sentence as ASAH2B in open-access papers:
ASAH2B is named in the same sentence as 2 diseases in open-access papers, as found by Europe PMC text mining. Sharing a sentence is not in itself a finding about the gene and the disease. The quoted sentences say what the papers report.
Alzheimer's dementia (1 paper, 2025). "We found that neutral ceramidase (ASAH2/ASAH2B) and sortilin-related VPS10 domain-containing receptor 2 (SORCS2) were significantly elevated in the serum of individuals who later developed Alzheimer's dementia." (PMID 40772191, 2025).
gout (1 paper, 2025). A condition characterized by painful swelling of the joints, which is caused by deposition of urate crystals. "Transcriptome-wide association studies highlighted several genes, such as SLC16A9 and ASAH2B, which showed significant expression patterns across various tissues, implicating metabolic and immune pathways in gout." (PMID 41075270, 2025).